EGFR (epidermal growth factor receptor)
Diseases named in the same sentence as EGFR in open-access papers (continued):
Sharing a sentence is not in itself a finding about the gene and the disease.
tumor (continued). "Classical GBMs are especially characterized by amplification in the epidermal growth factor receptor (EGFR), a receptor that has also been linked to tumor invasiveness." (PMID 28234925, 2017). "By contrast, variant VκF94A, displaying a 10-fold reduction in EGFR affinity, was inefficient in discriminating between the “target tumor” and “normal tissue” and overall exhibited similar target selectivity properties as the parental DuetMab." (PMID 28067257, 2017). "We correlated the number of CTCs detected by MCA with 6 clinicopathologic factors; namely, smoking history, previous treatment history, performance status (PS), histology, tumor stage, and epidermal growth factor receptor (EGFR) mutational status." (PMID 28640869, 2017). "One advantage of using metabolic parameters to predict EGFR mutation status is that these parameters provide direct measures of malignant lesions and can reflect tumor heterogeneity to a certain degree." (PMID 28422710, 2017). "IDF-11774 also inhibited the tumor growth of NCI-H1975 cells bearing an EGFR T790M mutation and wild-type KRAS." (PMID 28569777, 2017). "The aberrant activation of EGFR leads to activation of downstream signaling pathways associated with tumor growth and progression." (PMID 28407693, 2017). "The EGFR gatekeeper mutation p.T790M confers resistance to first- and second- generation EGFR-TKIs and prolongs the biologic condition of tumor addiction to EGFR transduction pathway in these tumors." (PMID 29156777, 2017). "Several research groups have detected EGFR mutations in plasma DNA or serum DNA and found a high correlation between EGFR mutations status in plasma or serum and tumor tissue." (PMID 28207548, 2017). "Previous studies have showed that EGFR mutation frequency in tumor is 28.4% (147/517) and plasma samples is 34.3% (79 of 230) in Chinese populations, respectively." (PMID 27791985, 2017). "EGFR mutations have been reported to constitutively cause EGFR autophosphorylation; the resulting poor patient survival rate is the major reason for drug resistance and tumor recurrence." (PMID 28787001, 2017). "Analysis of circulating free tumor-derived DNA (ctDNA) has been proposed as an alternative, minimally invasive method for the detection of EGFR mutations." (PMID 27980215, 2017). "Of 17 FFPE samples in which an EGFR exon 19 deletion was identified in the tumor, 17 were positive for the same mutation as that detected by the multiplex ddPCR assay." (PMID 28625519, 2017). "Of the 636 patients with activating mutations of EGFR exon, 168 were tumor-node-metastasis (TNM) stage III cases who received radical surgery." (PMID 28380449, 2017). "The activating mutations in the RAS pathway result in desensitization of tumor cell to EGFR inhibition." (PMID 26461472, 2017). "EGFR overexpression is related to poor prognosis, increased risk of tumor relapse, relative tolerance to treatment, and distant metastasis." (PMID 29137429, 2017). "Longitudinal EGFR mutation levels in plasma always correlated with tumor response ascertained by RECIST criteria." (PMID 28947971, 2017). "EGFR signaling is the growth factor system most often implicated in tumor progression through the activation of the receptor or its ligands, which leads to both mitogenesis and motility that correlate with tumor progression." (PMID 29237412, 2017). "Up to now, the only truly tumor-specific antigen for CAR is EGFR variant III (EGFRvIII) that is completely restricted to human cancer (most frequently observed in glioblastoma)." (PMID 29163850, 2017). "Detection of mutations that lead to acquired resistance to anti-EGFR therapy is clinically important but is limited in most cases by the unavailability of the metastatic tumor tissue." (PMID 28459822, 2017).
tumor (continued). "Several studies indicate RTKs are associated with MPM tumor progression, including epidermal growth factor receptor (EGFR), vascular endothelial growth factor receptor (VEGFR), insulin growth factor 1 receptor (IGF1R), and AXL." (PMID 29375377, 2017). "Tumor tissue genotyping is used routinely in cases of lung cancers to identify specific and targetable oncogenic alterations, including EGFR mutations and ALK rearrangements." (PMID 28392479, 2017). "The irreversible third-generation EGFR-TKI osimertinib that targets EGFR T790M shows promising responses against an activated mutant EGFR with a T790M mutation in a tumor xenograft model as well as in a clinical trial." (PMID 29050315, 2017). "In human HCC patients, EGFR mutations also cause increased tumor infiltration of immune cells and necrosis." (PMID 28871112, 2017). "The results indicated that if EGFR mutations were detected in the blood of aNSCLC patients, most likely they harbor EGFR mutations in tumor burden." (PMID 29100447, 2017). "Our study revealed that the sensitivity of ddPCR was 61.3% when tumor-tissue EGFR mutation was used as the gold standard." (PMID 28052016, 2017). "Four IgA antibodies directed against different tumor-associated targets for solid cancer indications (Her2, EGFR, TA-MUC1, TF) were biofunctional in ADCC assays using granulocytes as effector cells and corresponding target cell lines." (PMID 28952521, 2017). "A larger study of 40 EGFR-mutated advanced NSCLC patients compared the incidence of the T790M EGFR mutation in tumor samples (n=40), CTCs (isolated by CTC-chip) (n=28), and ctDNA (n=32)." (PMID 29312651, 2017). "Efficacy analyses were performed in NSCLC patients whose tumours harboured common EGFR mutations (Del19 or L885R) confirmed by tissue biopsy." (PMID 28006816, 2017). "This is a retrospective real world study looking at the proportion of patients with newly diagnosed stage III/IV adenocarcinoma of the lung whose diagnostic tumour sample underwent successful EGFR mutation analysis." (PMID 28367333, 2017). "In some of these patients, analysis of the tumor biopsies revealed an increased frequency of EGFR that is wild type for the T790 mutation as a mechanism of rociletinib resistance." (PMID 28431544, 2017). "In the Iressa Pan-Asia Study (IPASS), EGFR mutations were assessed by use of tumor tissue-derived DNA (n = 91) and cfDNA from pretreatment serum samples (n = 194)." (PMID 28099915, 2017). "Tumor samples from patients with resistance to anti-EGFR therapy such as gefitinib and erlotinib retained EGFR gene mutations such as T790M or exon 20 insertion." (PMID 29291022, 2017). "The patients with EGFR CNG had a much higher risk of tumor recurrence (OR =3.01, 95% CI =1.26-7.21, P =0.01)." (PMID 29190914, 2017). "This pathology-defined prognosis is also dependent on both tumor stage and the status of genetic mutations in the EGFR, KRAS, ALK, RET, and BRAF genes." (PMID 29137260, 2017). "Specifically, it was reported that five patients (14%) with lung ADC were found to have a diagnosis of SCLC in EGFR TKI-resistant tumor biopsies despite maintaining the original mutation and became sensitive to classical SCLC treatment." (PMID 27757846, 2017). "Due to their size, it was determined that small molecules would be most effective at targeting isolated changes in protein structure, and thereby differentiating between the tumor-associated mutant EGFR and the healthy wild type." (PMID 28611939, 2017). "Several studies have demonstrated that the EGFR mutations detected in plasma ctDNA are highly concordant with those detected in the tumor tissue of patients, indicating that ctDNA in plasma can serve as an alternative to tissue biopsy." (PMID 28978074, 2017).
tumor (continued). "Several FDG-PET/CT metrics regarding tumor heterogeneity correlated to EGFR mutation, but 1/COV appears to be the most reliable due to the lack of dependence on lesion size." (PMID 28881771, 2017). "Detecting EGFR T790M mutation in tumor tissue is challenging due to heterogeneity of the tumor, low abundance of the mutation and difficulty for re-biopsy in patients with advanced disease." (PMID 29246024, 2017). "In contrast, VAFs of the doublet EGFR mutations were highly concordant except for one specimen with 7.6% p.L858R and 65% p.T790M in a context of 11–30% estimated tumor cellularity, suggesting a germ-line p.T790M mutation." (PMID 29228562, 2017). "Several groups also reported that the sensitivity of cancer cells to EGFR-targeted therapy is associated with E-cadherin expression and other characteristics of typical “epithelial” tumor phenotypes." (PMID 29029445, 2017). "A non-invasive alternative to tissue is circulating tumor DNA (ctDNA) that has emerged recently and is reported as specific and sensitive biomarker for EGFR mutation detection." (PMID 29246024, 2017). "The PR was observed in an EGFR-TKI naïve patient who had a tumor with an EGFR-activating mutation (L858R)." (PMID 28144730, 2017). "The survival indices in high and low EGFR expression groups were further analyzed to search for possible association with tumor EGFR mutation status." (PMID 29246028, 2017). "In EGFR mutated tumours CpG island hypermethylation was shown to downregulated miR-200 family members in cells with gefitinib resistance and EMT features." (PMID 28771186, 2017). "The tumor tissue samples from these patients were evaluated by conventional ARMS PCR method to confirm their EGFR mutation status." (PMID 29340107, 2017). "In relation to the results of the present study, both uPAR, TF and EGFR fulfills the factors 1–5, which underlines the relevance of these receptors for targeted tumor imaging in OSCC." (PMID 28841839, 2017). "EGFR expression was reported to be correlated with more aggressive disease, increased risk of metastases, advanced tumor stage." (PMID 28938543, 2017). "The EURTAC trial demonstrated greater efficacy of erlotinib compared with chemotherapy for the first-line treatment of European patients with NSCLC harboring EGFR mutations in the tumor tissue." (PMID 28099915, 2017). "Here we provide evidence in support of a GBM tumor recurrence mechanism dependent on tumor heterogeneity and favored by tumor-specific chromosomes, herein EGFR-encoding DMs." (PMID 29113349, 2017). "Despite the extensive literature on EGFR endocytosis and intracellular sorting, the mechanisms underlying these processes and how they regulate EGFR signaling in normal and tumor cells are poorly understood." (PMID 29268862, 2017). "Increase in miR-9 expression in EGFR mutation bearing cell line leads to tumor suppression via direct regulation of FOXP1." (PMID 28868238, 2017). "There was not a significant association between survival outcomes and other clinical factors, including the Eastern Cooperative Oncology Group (ECOG) performance status (PS), EGFR mutation status, metastasis, age, sex, histology and tumor stage." (PMID 29156821, 2017). "Many methods have been used to detect cfDNA EGFR mutations, and their sensitivities have ranged from 35.6% to 81.8% for EGFR mutation detection in cfDNA compared with tumor tissue." (PMID 28052016, 2017). "Although with relatively small sample size, we consistently observed that levels of plasma EGFR mutations were highly correlated with changes of tumor diameter or development of new lesions." (PMID 28969034, 2017). "Our previous report showed detection of 0.001% prevalence of the EGFR T790M mutation among tumor cells." (PMID 28625519, 2017). "Both trials prospectively collected paired tumour and blood samples from patients for analysis of EGFR mutations." (PMID 28006816, 2017).
tumor (continued). "Some tumor-linked genetic alterations, such as in EGFR, BRAF, ALK, KIT, PDGFR, HER2, and KRAS, were only detected via ctDNA-based assays." (PMID 28392479, 2017). "Loss of sortilin in tumor cells promoted cell proliferation by sustaining EGFR signaling at the cell surface, ultimately accelerating tumor growth." (PMID 29084952, 2017). "The detection rates of EGFR mutation using cfDNA from blood samples compared with paired tumour samples were 28.6% (82 out of 287) in LL3 and 60.5% (202 out of 334) in LL6." (PMID 28006816, 2017). "In this study, the EGFR T790M mutation detection rate in tumor tissue obtained by digital PCR was 42.86% (18/42)." (PMID 28978074, 2017). "In our study, three out of five patients with multiple EGFR mutations exhibited inconsistent mutation subtypes between tumor tissue and matched plasma samples, which was also observed in previous studies." (PMID 28829813, 2017). "Translocated EML4-ALK transcripts and KRAS and EGFR transcripts harboring tumor-specific point mutations were detected by RT-PCR and deep amplicon sequencing." (PMID 28681241, 2017). "EGFR mutations were detected in 8 (27.6%) tumor tissue samples, of which, three harbored 19del, two harbored L858R and one harbored 20ins." (PMID 28107191, 2017). "Epidermal growth factor receptor overexpression by tumor cells is associated with uncontrolled proliferation, angiogenesis, anti-apoptotic signals, metastization, and invasiveness." (PMID 28348561, 2017). "Our review provides an overview of various commonly used platforms for detecting EGFR T790M mutation in tumor tissue and plasma." (PMID 29246024, 2017). "The EGFR signaling has been demonstrated to contribute to the enhancement of BCSC self-renewal induced by versican or by tumor-associated macrophages." (PMID 29100291, 2017). "In EGFR-mutated tumours treated with the first (erlotinib, gefitinib) or second (afatinib) generation EGFR tyrosine kinase inhibitors, the most frequent mechanism of resistance is a secondary mutation in exon 20 of the EGFR-gene; T790M." (PMID 28680534, 2017). "The epithelial-mesenchymal transition (EMT) of tumor cells results in stem cell-like characteristics and causes resistance to many anticancer drugs, including EGFR TKIs." (PMID 29140271, 2017). "Older patients were also more likely to have a tumor with activating EGFR mutation, with a prevalence per age quartiles increasing from 7.7% in younger patients (< 61 years) to 15.6% in older patients (> 76 years)." (PMID 28881604, 2017). "In a study of 26 FFPE tumor specimens, activating EGFR mutations associated with sensitivity to the EGFR TKI therapy were detected in eight cases." (PMID 28137276, 2017). "Gefitinib and afatinib are drugs specifically targeting the tyrosine domain of EGFR that inhibit the function of EGFR and cause tumor cell death." (PMID 29163769, 2017). "Compared to the second-generation TKIs, the third-generation EGFR-TKI selectively target T790M mutations, and irreversibly bind to EGFR ATP pocket, inhibiting EGFR kinase phosphorylation and the activation of downstream tumor signaling pathway." (PMID 29050366, 2017). "Abnormal EGFR signaling is the central mechanism for various cancers, often arising from mutated EGFR that triggers downstream signaling cascades, resulting in aberrant cellular growth and ultimately tumor formation." (PMID 27956147, 2017). "Both the detection rate for plasma cfDNA EGFR mutations and the detection rate for tumor-tissue EGFR mutations correlated with gender and smoking history." (PMID 28052016, 2017). "EGFR is a tyrosine kinase receptor (TKR) whose expression in solid tumors is often associated with tumor development and progression." (PMID 31548531, 2017). "In our study, the seven included patients had primary tumor tissues or BMs diagnosed, EGFR mutation(5, 19 deletion/2, 20 deletion) and received gefitinib as primary treatment." (PMID 28915686, 2017).
tumor (continued). "Compared to the matched tumor tissues, the sensitivity and specificity for EGFR mutation detection in plasma by ADx-SuperARMS were 82.0% (50/61) and 100% (48/48), respectively." (PMID 28829813, 2017). "Direct sequencing of DNA extracted from fresh or formalin-fixed, paraffin-embedded tumor tissue is the historical standard for EGFR mutation testing." (PMID 28938658, 2017). "ERMS tumor also harbored additional gene alterations: low amplification of EGFR, PDGFRA, and CDK4 genes, and loss of heterozygosity of CDKN2A and 19q12-19q13.43 chromosomal regions." (PMID 28222777, 2017). "This rich data set offers an opportunity to examine the likelihood KRAS mutations confer acquired resistance to an anti-EGFR antibody and provided a platform to examine variables affecting tumor-doubling times." (PMID 28981524, 2017). "First, analyses from aspiration biopsies cannot reflect the EGFR mutation status of a whole tumor due to its heterogeneity." (PMID 28489575, 2017). "For a patient whose tumor is positive for an EGFR mutation, erlotinib, afatinib or gefitinib is recommended as the first-line therapy." (PMID 29232915, 2017). "They found EGFR gene deregulation in 25 out of 36 primary tumours and 29 out of 36 metastases, KRAS mutations in 16 out of 37 cancers and in 15 out of 37 metastases, and BRAF mutations in 2 out of 36 cancers and 2 out of 36 metastases." (PMID 28097409, 2017). "In the 109 tumor tissue-plasma paired clinical samples, 98 carried the same EGFR mutation status in both samples, giving a concordance of 89.9%." (PMID 28829813, 2017). "Further logistic regression analysis in our experiment showed that the EGFR mutations under study were associated with gender and tumor type." (PMID 28684733, 2017). "Disease control rate of 81.6% was higher than that found in the group with EGFR activating mutations in primary tumor tissues based on TTG." (PMID 29290998, 2017). "In particular, earlier studies of the anti-EGFR blocking antibody cetuximab, have suggested that increased tumor expression of HLA class I is associated with positive clinical response." (PMID 29056908, 2017). "This experimental system was further employed in our current project on identification of tumor mutations with targeted resequencing of EGFR (epidermal growth factor receptor) gene." (PMID 28583065, 2017). "For example, when resistance to cetuximab is caused by the EGFR S492R mutation, subsequent treatment with the alternative EGFR inhibitor, panitumumab, can lead to transient tumor regression." (PMID 28002810, 2017). "In humans EGFR is a potent driver of oncogenesis; over-expressed in a range of tumours; and is associated with worse overall survival." (PMID 29069805, 2017). "Epidermal growth factor receptor (EGFR) is one of the most common oncogenes, activating mutations of which drive tumor growth in NSCLC." (PMID 28881820, 2017). "Compared with tumor tissue, the sensitivity and specificity for EGFR T790M mutation detection in plasma by ddPCR were 66.7% (6/9) and 71.4% (5/7), respectively." (PMID 28000387, 2017). "Among RTKs, uPAR is implicated in an extensive cross-talk with epidermal growth factor receptor (EGFR) that mediates the shift from tumor cell dormancy to proliferation." (PMID 28839232, 2017). "This is consistent with a previous study, reporting that patients with both tumor tissue and plasma EGFR activating mutations showed superior progression-free survival (PFS) and overall survival (OS) compared to patients with tumor tissue mutations only." (PMID 29340107, 2017). "Sensitivity, defined as the proportion of tumor tissue-based mutations that were detected by both assays, was 100% for EGFR, although there was only one EGFR alteration." (PMID 29137355, 2017).